CTCF (CCCTC-binding factor)
Diseases named in the same sentence as CTCF in open-access papers (continued):
Sharing a sentence is not in itself a finding about the gene and the disease.
tumor (continued). "There was a significant correlation between expression of CTCF and histological grades; lower expression was associated with grade 3 tumours." (PMID 15354217, 2004). "Besides its role in loop extrusion, CTCF acts as an activator, repressor, and insulator; it is also associated with regulation of chromatin architecture, DNA methylation, and tumor suppression." (PMID 37047368, 2023). "Thus, we supposed that BC tumor with CTCF mutations were more likely to develop metastasis, even though the number of patients in the baseline cohort was limited." (PMID 35971249, 2022). "The mechanism of the tumour suppressor action of CTCF might involve deregulated DNA methylation – the loss of CTCF binding can result in hypermethylation of CpGs." (PMID 35993175, 2022). "Some tumor cell mutations occur within the zinc fingers of CTCF and may selectively perturb certain loops, as they affect CTCF binding at only a subset of sites." (PMID 35011637, 2021). "Tumour-specific mutations in CTCF were described almost two decades ago." (PMID 34657170, 2021). "Interestingly, structural DNA changes induced by CTCF have also been implicated with telomere maintenance and tumor cell immortality as CTCF is supposed to prevent telomere DNA damage signaling." (PMID 31736271, 2020). "In tumour DNA, there was a similar ratio of mutant to wild-type alleles for missense mutations and inactivating mutations (37.6±3.2% and 32.8±2.3%, respectively, mean±s.e.m) consistent with monoallelic mutation of CTCF." (PMID 28319062, 2017). "The mutational load at CTCF-binding sites appears to be dominantly determined by replication timing and the mutational signature of the tumor sample in question, suggesting that selectively neutral processes underlie the unusual mutation patterns seen at CTCF sites across tumor types." (PMID 27294413, 2016). "SUMOylation of CTCF has been associated with its tumor suppressive function in c-myc expression." (PMID 26833217, 2016). "Staining of CTCF was detected in the nuclei and cytoplasm of the malignant cells, but no significant loss or decrease of expression was noticed in association with any specific tumour type." (PMID 15354217, 2004). "Secondly, if this cytoplasmic expression of CTCF was an indication of mutation or inactivity that has any significant tumour suppressor role in a particular tumour type, we would expect an association between the pattern of expression (nuclear, cytoplasmic or reduced) and the tumour type." (PMID 15354217, 2004). "Furthermore, the interaction between CTCF and hypoxia-responsive pathways, such as those governed by hypoxia-inducible factors (HIFs) 40, may unveil novel mechanisms underlying tumor progression and resistance to therapeutic interventions." (PMID 40959269, 2025). "Furthermore, this study indicated that CTCF mutations were enriched in tumor samples of metastatic BC compared to local BC (2% vs. 0.9%, P < 0.01), and it was supposed that CTCF mutation might be a metastatic driver." (PMID 35971249, 2022). "Moreover, an in vivo tumor growth assay confirmed that the inhibition of the Hedgehog signaling pathway with JK184 recovered the stimulation of cell proliferation caused by upregulated CTCF (n=5/group)." (PMID 32688344, 2020). "Functionally, CTCF modulated neutrophil survival, ribosomal function, and recruitment toward tumor cells through MIEN1." (PMID 40959269, 2025). "BORIS regulates tumor initiation and progression through various mechanisms, including competitively binding to CTCF's DNA targets and interfering with CTCF function, participating in epigenetic regulation, and promoting the generation of tumor stem cells." (PMID 39905312, 2025). "In an orthotopic CRC mouse model, CTCF-over-expressing TANs increased tumor growth and TAN infiltration, which was attenuated by MIEN1 knockdown or IL-1β neutralization." (PMID 40959269, 2025).
tumor (continued). "This study found that si-CTCF significantly reduced tumor tissue size, suggesting a potential relationship with TIICs and their interactions." (PMID 39623397, 2024). "IHC staining experiments consistently confirmed that, CTCF knockdown partially reversed the regulation of RPL35A overexpression on the proliferation marker KI67 in tumour tissues." (PMID 38436544, 2024). "To assess the impact of CTCF knockdown on tumor growth, we established a subcutaneous EC model in thymus-free nude mice using EC cells stably transfected with sh-NC and sh-CTCF." (PMID 39623397, 2024). "In glioma and gastrointestinal stromal tumors (GISTs), 2-HG displacement of CTCF allows enhancers once insulated from nearby proto-oncogenes to activate their expression to promote tumor growth and progression." (PMID 37884500, 2023). "Mechanistically, FOXD3-AS1 interacts with poly (ADP-ribose) polymerase 1 (PARP1) in nucleus to prevent poly (ADP-ribosyl)ation and activation of CTCF, resulting in decreasing of downstream tumor-suppressive genes." (PMID 36923440, 2023). "HNF4A-AS1 binds to heterogeneous nuclear ribonucleoprotein U (hnRNPU) to promote its association with CCCTC-binding factor (CTCF), resulting in transactivation of CTCF and transcriptional alteration of HNF4A and other genes associated with tumor progression." (PMID 36923440, 2023). "Alterations of the chromatin structure have been reported in many tumour types and are due to altered CTCF or cohesin binding, chromosome structural variants or aberrant histone modifications." (PMID 36922594, 2023). "The changes we observe agree with experiments showing that the R339Q mutant diminishes DNA binding, impairs the CTCF tumor suppressor activity, and affects its regulatory transcriptional activity." (PMID 37047368, 2023). "Based on the pathway’s deregulated and invasive phenotype, we posit that CTCF CNL plays a more important role in tumor progression within breast tissue than tumor initiation." (PMID 36037342, 2022). "After 110 fields were analysed, the PDAC patients were divided into two groups based on the median density of CTCF+ TAM infiltration (the percentage of CTCF+ TAMs number in total CD206+ cells number) in the tumour microenvironment in 110 PDAC patients." (PMID 35184402, 2022). "Treatment with FOXD3‐AS1 constructs or siRNA targeting PARP1 or CTCF reduces tumor growth and prolongs survival in tumor‐bearing nude mice xenografts." (PMID 35592755, 2022). "Here, we discovered a novel mechanism of epigenetic modulation, that results in polarization of TAMs towards pro‐tumour M2 phenotype: CTCF binds to the overlapped promoter region of PACERR and PTGS2, leading to the transcription of PACERR." (PMID 35184402, 2022). "And similar results were validated in these findings through C57BL/6 mice indicate that CTCF is a critical regulator promoting the M2 polarization and pro‐tumour functions of macrophages." (PMID 35184402, 2022). "Postulation of a dependency between the presence of the chromatin domain-anchoring protein CTCF and the tendency of DSBs to cluster within a domain was sufficient to recapitulate the experimental data of both tumor cells." (PMID 35409255, 2022). "Subsequently, an analysis through the Vesiclepedia database found that CTCF was enriched in tumor-derived exosomes." (PMID 35693981, 2022). "Up-regulation of ten DEGs in PAAD tumor is in concordance with the up-regulation of master regulators CTCF, IRF1, and KLF4, while POLR2A and STAG1 remain unchanged." (PMID 35453789, 2022).
tumor (continued). "In vitro and in vivo experiments demonstrated that CTCF promotes the M2 polarization and pro‐tumour functions of TAMs." (PMID 35184402, 2022). "Despite such clear evidence for a tumor suppressive role for CTCF in hematopoietic tissue, the importance of physiological levels and functionality of CTCF for the prevention of solid tumors remains ambiguous." (PMID 36037342, 2022). "Although CTCF is essential for cell survival, inadequate haploid CTCF is related to tumor development and hypermethylation." (PMID 35693981, 2022). "An important tumor suppressor that is involved in epigenetic regulation is CCCTC-binding factor (CTCF)." (PMID 34065345, 2021). "Extensive characterisation of the action of CTCF in vitro and in vivo has led to its classification as a haploinsufficient tumour suppressor gene." (PMID 34657170, 2021). "Further evidence regarding its tumor suppressive function was demonstrated by the discovery that CDKi P16 is also under transcriptional control of CTCF." (PMID 34065345, 2021). "CTCF is proposed as a tumor suppressor in multiple cancers, thereby our qRT-PCR assay revealed its downregulation in RCC cell lines and tissues." (PMID 34775467, 2021). "We next examined cell growth and showed that WT CTCF overexpression suppressed cellular proliferation (p < 0.0001) consistent with it being a tumour suppressor and as previously shown." (PMID 34657170, 2021). "Mechanistically, FOXD3-AS1 interacts with poly (ADP-ribose) polymerase 1 (PARP1) to repress the poly(ADP-ribosyl)ation and activation of CCCTC-binding factor (CTCF), leading to de-repression of downstream tumour-suppressive genes." (PMID 33671241, 2021). "To gain mechanistic insights into CRE30 and long-range gene regulation, we first verified the recruitment of CTCF on CRE30 segments in different tumor types and loci using ChIP." (PMID 35127534, 2021). "The hypomethylation of CBS promotes a higher occupancy by CTCF, resulting in de novo formation of TAD boundaries causing deregulation of gene expression often linked to tumor suppressor silencing." (PMID 34332627, 2021). "It has been reported that the CTCC-binding protein (CTCF) acts as a tumor suppressor gene by regulating the expression of tumor-related genes." (PMID 33256112, 2020). "CTCF expression in tumor and adjacent normal tissues was analyzed by qRT-PCR and western blot assays, and the results showed that CTCF was upregulated in tumor specimens." (PMID 32688344, 2020). "Mass spectrometry analyses indicated that several proteins were pulled-down with PD-L1, among which, we selected CTCF, which is stemness-related and involved in tumor cell self-renewal." (PMID 33204322, 2020). "CTCF target genes that have an important impact on tumor phenotype and prognosis were validated using GC cell line experiments." (PMID 33665169, 2020). "Most of all, subcutaneous xenotransplanted tumor model of human CRC in nude mice further confirmed that CTCF enhanced 5-FU resistance via activating Hedgehog signaling pathway." (PMID 32688344, 2020). "Then, we assessed the expression level of CTCF in tumor and paracancerous normal colorectal tissues." (PMID 32688344, 2020). "After siCTCF treatment, Western blot revealed that the expression of CTCF, pFOXO1a and pFOXO3a was down‐regulated, while that of FOXO1a and FOXO3a was up‐regulated in tumour issues." (PMID 30873749, 2019). "The results showed that compared with tissues in cells adjacent to the tumours, the mRNA of CTCF was richly expressed in tumour tissues." (PMID 30873749, 2019). "After siCTCF treatment, Western blot showed that the protein expression of CTCF in tumour tissues in nude mice was inhibited, the expression of FOXO1a and FOXO3a was up‐regulated, while that of pFOXO1a and pFOXO3a was down‐regulated." (PMID 30873749, 2019).
tumor (continued). "The evidence described here argues that diverse human tumor cell super-enhancers depend on the MYC CTCF site for optimal levels of enhancer-promoter looping and mRNA expression." (PMID 29641996, 2018). "Our previous studies first demonstrated the growth inhibitory effects of CTCF in vitro and subsequently confirmed that CTCF acts as a tumour suppressor gene in vivo by suppressing tumour growth." (PMID 30513694, 2018). "Both CTCF-bound and non-CTCF anchor points harbour an excess of SV breakpoints in multiple tumour types and are prone to double-strand breaks in cell lines." (PMID 30060743, 2018). "Our results confirm the absolute requirement for CTCF expression in somatic cells and provide definitive evidence of CTCF’s role as a haploinsufficient tumour suppressor gene." (PMID 30513694, 2018). "Paradoxically, after CTCF knockdown here, and in corroboration of our previous CTCF overexpression study we observed tumour suppressive phenotypes for CTCF in K562 cells." (PMID 30513694, 2018). "All three sites were found to be occupied by CTCF in a wide variety of normal cells and tumor cells, and this binding pattern is shared across species." (PMID 29641996, 2018). "Previous studies have demonstrated that the expression pattern and role of CTCF vary in different tumor types." (PMID 28977939, 2017). "In summary, this study presents a novel strategy to develop biomarkers for tumor prevention and treatment based on CTCF DNA-binding sites." (PMID 29371978, 2017). "We hope that our study will serve as a starting point for more extensive and in-depth studies to fully estimate the potential of CTCF DNA-binding sites as methylation biomarkers for clinical applications in tumor prevention and treatment." (PMID 29371978, 2017). "CTCF was originally discovered as a candidate tumor suppressor, given its ability to bind to the promoter of the oncogene c-myc to inhibit its expression." (PMID 29212169, 2017). "To confirm the tumor suppressor role of CTCF in vivo, we established a xenograft model by inoculating nude mice with MDA-MB-231-CTCF or control cells." (PMID 29212169, 2017). "CTCF is a haploinsufficient tumour suppressor gene with diverse normal functions in genome structure and gene regulation." (PMID 28319062, 2017). "Among tumours that developed metastases, two of seven showed CTCF deletion including a mixed grade 3 endometrioid/clear cell tumour and a grade 2 endometrioid tumour." (PMID 28319062, 2017). "Loss in CTCF copy number occurred in 7.0% of endometrioid and 65.5% of serous subtype tumours, indicating that CTCF genetic deletion was more common in poorer prognosis serous subtype tumours (Fisher’s exact test, P<0.001)." (PMID 28319062, 2017). "To date, no homozygous deletion resulting in complete inactivation of CTCF has been reported in tumours." (PMID 28319062, 2017). "The in vivo assay indicated that enforced CTCF expression suppressed tumor growth significantly in the xenograft nude mouse model." (PMID 29212169, 2017). "We found that CTCF mRNA expression levels were approximately 2-fold higher in tumor specimens compared with the paired normal tissues (n=10, P=0.0025)." (PMID 28977939, 2017). "The authors also showed that CTCF is frequently hemizygous in human tumours, and interestingly, among the human tumours investigated, the H19 locus was frequently found to be hypermethylated, as was the case in the hemizygous mice." (PMID 28587163, 2017). "The results of the IHC analysis also demonstrated significantly increased expression of CTCF in tumor specimens compared with the matched normal tissues (n=20, P=0.001)." (PMID 28977939, 2017). "Overall, 22.6% of tumours harboured a coding mutation in one of the seven Mut-driver genes involved in chromatin function (KMT2C, ARID1A, NCOR1, CTCF, KDM6A, PRBM1 and TBL1XR1)." (PMID 27161491, 2016). "It has been shown that the insulator binding protein CTCF is involved in the epigenetic regulation of tumor suppressor genes." (PMID 26833217, 2016).
tumor (continued). "CTCF was recently demonstrated to be a tumor suppressor and its haploinsufficiency to lead to an increased variability in CpG methylation genome-wide." (PMID 27602765, 2016). "The gene with the highest signal of positive selection in the CNN state was CTCF, a gene that has indeed been proposed as a haploinsufficient tumor suppressor gene." (PMID 28027311, 2016). "HMGA2 disrupts binding of CTCF, a protein involved in maintenance of chromatin topology which insulates tumour suppressor genes and which has an inverse occupancy pattern with DNA methylated regions." (PMID 25492890, 2015). "CTCF is known to regulate the expression of diverse tumour suppressor genes by directly binding to promoter sequences." (PMID 26443201, 2015). "For ERG and CTCF, we further validated binding at a subset of these regions in primary tumor specimens by ChIP–qPCR (Fig EV1B–E)." (PMID 26412853, 2015). "Undoubtedly, our results introduce a controversial role for the tumor suppressor CTCF in apoptosis and proliferation." (PMID 24393203, 2014). "Previously, it has been reported that the CTCCC binding protein (CTCF) is involved in the epigenetic regulation of tumor suppressor genes." (PMID 25352953, 2014). "In contrast to previous findings suggesting divergence in the roles of BORIS and CTCF, recent evidence has shown that both proteins are able to mediate similar growth and tumour suppressor functions and both provide a protective effect during apoptosis." (PMID 24279897, 2013). "CTCFL, also known as BORIS, is a transcriptional regulator; it directs epigenetic reprogramming at CTCF target sites in normal and tumor tissues." (PMID 23592437, 2013). "Several studies have shown that CTCF plays important roles in processes such as genetic imprinting, X-chromosome inactivation and preventing aberrant transcriptional silencing of tumor suppressor genes." (PMID 22879976, 2012). "It is now known that a multifunctional CCCTC-binding factor (CTCF) can serve as a barrier against the spread of DNA methylation and histone repressive marks over promoter regions of tumor suppressor genes." (PMID 22277129, 2012). "CTCF can also serve as a barrier against the spread of DNA methylation and histone repressive marks over promoter regions of tumor suppressor genes." (PMID 23056006, 2012). "CTCF-like, or BORIS, is thought to antagonise CTCF and has been found in normal testis, ovary and a large variety of tumour cells." (PMID 22724006, 2012). "After nuclear transfer, the abnormal tumor epigenotype was corrected by in vitro reprogramming, suggesting that LOI is associated with the loss of activity of non-CTCF trans-imprinting factor(s) that are either inactivated or mutated in tumors." (PMID 23171475, 2012). "Clinical translation could be accelerated through biomarker-guided cohort stratification in immunotherapy trials, coupled with exploration of small-molecule inhibitors targeting hypoxia-induced CTCF stabilization to disrupt Neu2-mediated tumor progression." (PMID 40959269, 2025). "Notably, CTCF emerged as the top-ranked motif in all six tumor types, which highlighted its pivotal role for CTCF binding at sites where the average DNA methylation levels remain unchanged yet methylation concurrence was disrupted." (PMID 40806343, 2025). "These genes were significantly correlated with patient outcomes, which implied that their dysregulation at MCR-depleted CTCF-bound loop anchors may contribute to tumor progression or aggressiveness." (PMID 40806343, 2025). "Compared to WT mice, tumors in heterozygous CTCF mice exhibit higher invasiveness in terms of invasion, metastatic spread, and mixed epithelial/stromal differentiation, confirming CTCF as a haploinsufficient tumor suppressor." (PMID 39623397, 2024). "The present study showed that CTCF knockdown could significantly restrain EC cells from migrating and invading and inhibited tumor growth in EC-bearing mice, indicating CTCF may play an anti-tumor effect in EC." (PMID 39623397, 2024).